IL4 (interleukin 4)
Diseases named in the same sentence as IL4 in open-access papers (continued):
Sharing a sentence is not in itself a finding about the gene and the disease.
cancer (continued). "In addition, the involvement of certain interleukins including IL-6, IL-4, IL-17A and IL-32β in some EMT pathways signifies their specific contribution in metastastic processes, thereby warranting further work into the development of diagnostic and immunotherapeutic tools in cancer." (PMID 25590298, 2015). "Other important pathways manly related to angiogenesis, oxidative stress like IL4 and ERK1/2 signaling, cell migration and proliferation like TGF-beta and cancer immunosurveillance signaling were down-regulated after the treatments." (PMID 24756038, 2014). "The rationalization for this treatment is based on the observation of the inhibitory effect of IL-4 on NHL B cells and cancer cells in vitro." (PMID 25541655, 2014). "It should be mentioned that the IL-4 mRNA was increased in PBMC, while expression of IL-4 protein in plasma was unchanged in cancer patients." (PMID 25144454, 2014). "Myeloid DC obtained culturing peripheral blood monocytes with IL-4 and granulocyte-macrophage colony-stimulating factor (GM-CSF) (IL4-DC) have been implied in immunotherapy of cancer and, most recently, of HIV infection." (PMID 24373498, 2013). "Suppressed levels of Th1 cytokines (IFN-γ, IL-12, TNF-α) and elevated levels of Th2 cytokines (IL-4, IL-10, TGF-β) have been seen in patients with cancer, while the opposite pattern is seen in healthy individuals." (PMID 23730621, 2013). "In our previously published work we had shown that this cytokine combination (GM-CSF, IL-4, TNF-α ± IFN-α) was capable of generating DCs in vitro from CD14+ monocytes obtained from healthy individuals and patients with cancer." (PMID 19298672, 2009). "Autologous DCs were generated from 10 patients (HLA-0201) with advanced cancer by culturing CD14+ blood monocytes in the presence of GM-CSF and IL-4 supplemented with TNF-α [DCT] or TNF-α and IFN-α [DCTI]." (PMID 19298672, 2009). "For instance, IL-4 and IL-13, increase the expression of 15-LOX-1 and -2 in a number of cell types, including monocytes/macrophages, T lymphocytes and several cancer cell lines." (PMID 19296842, 2009). "When we cocultured these APG-2575-treated cancer cells with genetic alteration of BCL-2 with IL-4-activated macrophages, we found that neither downregulation nor upregulation of BCL-2 in the cancer cells altered the expression of M1/M2-related markers." (PMID 38062129, 2024). "Human-derived cytokines interleukin-2 (IL-2), IL-4, IL-6, IL-12, IL-10, tumor necrosis factor α (TNF-α), and interferon-γ (IFN-γ) could be detected in all cancer cell–bearing mice by cytokine level measurement." (PMID 39606226, 2024). "Indeed, the expressions of both cellular and exosomal PD-L2 in cancer cells were upregulated by INF-γ and IL-4." (PMID 39511147, 2024). "In previous studies, a negative relationship between psychological symptoms and IL-4 in cancer patients has been observed." (PMID 39355088, 2024). "IL-4 belongs to the interleukin family and interleukins are small molecular proteins secreted mainly by CD3 + and CD4 + T lymphocytes, which mediate the necessary interactions for the progress of cancer cells." (PMID 37007080, 2023). "As IFNγ has a direct antiproliferative effect on cancer cells, we used controls that included spheroids with IFNγ/Pam3SCK4 or IL-4 but without macrophages." (PMID 37445941, 2023). "has described, and largely proved, that interleukin 4 (IL‐4)‐induced gene 1 (IL4I1), a secreted enzyme belonging to the L‐amino‐acid oxidase family, was able to promote Aryl‐Hydrocarbon Receptor (AHR)‐driven cancer immunosuppressive ability." (PMID 38117000, 2023). "Cytokine stimulation in HLH patients reduces CD47 expression, interleukin 4 (IL-4), IL-7, and IL-13 influence CD47 expression on Sezary cells, and the expression level of CD47 in cancer cells is regulated by miR-133a, MYC oncogene, and the ERK signaling pathway." (PMID 37241964, 2023).
cancer (continued). "This decrease in MNCs proliferation may be associated with the presence of Th2-type immunosuppressive cytokines, such as IL-4, IL-10 and TGF-β, which are mainly responsible for immunosuppression in different types of cancer." (PMID 36661506, 2022). "IL-2, IL-4, and IL-12 may need to be modified or combined with other adjuvants, such as Montanide ISA-51 or GM-CSF in peptide-based cancer vaccine therapies to increase effectiveness." (PMID 35967400, 2022). "The expression level of IL6 was also significantly higher in TNBC compared with non-TNBC tissues, whereas IL4 level was not different between cancer types." (PMID 35960749, 2022). "IL-4 promotes TH2-type inflammation and TH9 cell polarization, which promotes cancer growth." (PMID 36157224, 2022). "These experimental findings may have translational relevance in cancer: there is the possibility that CSF1, in conjunction with basophil-derived IL-4/IL-13, might enhance the M2-like/TAM polarization of macrophage in TME." (PMID 36578500, 2022). "To investigate the role of ferrichrome on macrophage-induced migration and invasion of cancer cells, we first obtained macrophage conditioned media (CM) by culturing RAW264.7 cell line in the presence of vehicle (VCM), IL-4 (IL-4-CM) or IL-4 + ferrichrome (FCM) for 24 h." (PMID 36333531, 2022). "This included decreased anti-inflammatory factors such as IL-4, IL-13, M-CSF and CXCL12 and antitumor factors SCF, FLT-3L and IL-25 that could contribute to cancer progression and metastasis." (PMID 34575976, 2021). "Also, the key roles of the genes selected by the Laplacian score including IFN-γ, Foxp3, IL-4, BCL-2, Oct4 and survivin in the development of various cancers and their prognostic value have been clinically confirmed." (PMID 34181334, 2021). "Biological pathway analysis revealed the downregulated DEGs are mainly enriched in vitamin A and carotenoid metabolism, wnt signaling, cancer pathway, TLR4 signaling and tolerance, G13 signaling pathway, tryptophan metabolism, differentiation pathway, IL-3, IL-4 signaling pathway." (PMID 34960172, 2021). "In nonmetastatic cancer patients, T cells were negatively correlated with IL-6 and IL-10 and were positively correlated with IL-4 and TNF-α." (PMID 34712741, 2021). "Moreover, it has been proved that IL-4 induces an expression of antiapoptotic proteins, such as Bax, BCL-xl, xFLIP, and contributes to sustained cancer growth through the induction of expression of glucose transporter—GLUT1." (PMID 34071442, 2021). "Intriguingly, MDSCs are also implicated in MET in cancer cells and during the formation of premetastatic niches; MDSCs reach the niche before the cancer cells and promote their seeding by secreting immunosuppressive factors, including S100A8/A9, FGF-β, IL-10, and IL-4." (PMID 34576042, 2021). "Target cancer antigens that have been investigated include CD22, mesothelin, CD25, CD30, CD33, Glypican 3, carcinoembryonic antigen, and receptors for EGF, IL4, IL6, and IL13." (PMID 32630017, 2020). "Basophils reportedly interact with and stimulate B cells through CD40L and release of IL-4, IL-6, IL-13, BAFF, and histamine, all of which may augment B cell proliferation, survival and antibody responses against cancer." (PMID 32645919, 2020). "When MDMs were not opsonized, those polarized with IL-4 and M-CSF more actively phagocytosed cancer cells than did LPS- and IFN-γ-stimulated MDMs (compare “non-ops” lanes)." (PMID 30760760, 2019). "IL4 and IL13 bind to IL4Rα and IL13Rα1 chains, forming functional structures in cancer cells." (PMID 31540495, 2019).
cancer (continued). "Moreover, our functional data underscore that TBX21 promoted IL-4 expression and IL-4 signaling is indispensable for TBX21-mediated cancer cell stemness." (PMID 29615105, 2018). "IL-1β, IL-4, TGF-β1a, and IL-10 mRNA levels were unaffected by cancer cell EVs." (PMID 28947958, 2017). "Stimulated production of Th1 effector cytokine IFN-γ by CD4+ T cells was not impacted by cancer while production of the Th2 effector IL-4 was significantly decreased in cancer septic mice." (PMID 27018973, 2016). "Results from these two large randomized aerobic exercise intervention trials suggest that aerobic exercise does not alter IL‐10 or IL‐4 in a manner consistent with chronic disease and cancer prevention." (PMID 27485297, 2016). "Our cytotoxicity assay revealed that both [AP1-V12]6 and [V14]6 polymers are nontoxic to cancer cell, as both polymers have least effect on cell viability or proliferation in absence of external IL-4 supplements." (PMID 24339977, 2013). "As the cancer progressed at the tongue root, the percentage of CD3+CD4+ T lymphocytes and NK cells and the levels of IFN-γ and IL-2 decreased gradually, while the percentage of CD3+CD8+ T lymphocytes and the levels of IL-4 and IL-10 increased." (PMID 17338814, 2007). "Notably, the majority of IL-4+/CD11b+ myeloid cells were located within the cancer cell nests and not in the CK-negative stromal tissue compartment." (PMID 40091029, 2025). "Furthermore, the levels of multiple cytokines, including IL-2, IL-4, IL-6, IL-10, TNF, and IFN-γ in the supernatant of the OHSV2-DSTEFAP5/CD3 group co-cultured with cancer cells and fibroblasts, showed a significant increase compared to groups with either cell type alone." (PMID 40406146, 2025). "CD4+ Th cells assist in activating CD8+ CTLs and also produce cytokines that indirectly contribute to the anti-cancer immune response, common pro-inflammatory cytokines include IL-1, IL-6, IL-8, and tumor necrosis factor-α (TNF-α), while common anti-inflammatory cytokines include IL-4 and IL-10." (PMID 40881864, 2025). "Therefore, radiotherapy combined with IL-4 signaling inhibitors and/or second-generation M1-polarized CAR or in combination with medicine targeting cancer Tregs might become a next-generation regimen for radioimmunotherapy." (PMID 38474078, 2024). "Recently, it has been shown that anti-inflammatory cytokines (IL-10 and IL-4) are protective against CIPN; however, systemic use of IL-10 in general has had poor clinical outcomes as it can promote the progression of cancer and propagate chronic viral infections." (PMID 38330029, 2024). "PA-MSHA has demonstrated positive anti-cancer effects across various cancer types by interacting with the immune system in several ways: it induces M1 polarization of macrophages, Th1 immune response promotion, and increases the secretion of IFN-γ while reducing the production of IL-10 and IL-4." (PMID 38339275, 2024). "Unlike M2 macrophages, M1→M2 began to secrete certain IL-4-induced chemokines only after co-culture with cancer cell spheroids, for instance, CCL17 (M1→M2: 0.02 ng/mL; S + M1→M2: 0.12 ng/mL, p = 0.0004) and CCL24 (M1→M2: 0.5 ng/mL; S + M1→M2: 2.4 ng/mL, p = 0.0016)." (PMID 37445941, 2023). "Interestingly, BAM15 treatment enhanced the OCR in LPS-induced M1 polarization, but it did not affect the OCR in M2 macrophages induced by IL-4 and cancer cell supernatants." (PMID 38140036, 2023). "Similar to IL-4, currently there are no ongoing clinical trials involving IL-5 or IL-9 in cancer treatment, likely a reflection of our current inadequate understanding of whether they would promote or inhibit cancer under different contexts." (PMID 37455828, 2023). "Previous reports indicate that the removal of MMP9 expression increases the secretion of IL-4 and IL-13 in the inflammation of respiratory airways, suggesting the existence of a self-regulatory loop between IL-13 and MMP9 expression to sustain cancer-enabling inflammation." (PMID 37963919, 2023).
cancer (continued). "However, IL-2, IL-4, and IL-12 are not very effective when used alone in peptide-based cancer vaccines." (PMID 35967400, 2022). "Therefore, IL-4 generally does not have a good antitumor effect in cancer vaccines as an adjuvant alone." (PMID 35967400, 2022). "Thus, IL-2, IL-4, and IL-12 are not very effective when used alone in peptide-based cancer vaccines." (PMID 35967400, 2022). "IL-4 was able to stimulate phosphorylation of STAT6 at significantly lower doses than IL-13 in the human epithelial carcinoma cell line A549, suggesting that STAT6 may not be the main downstream molecular target of IL-13." (PMID 35578342, 2022). "With the same cytokine receptor γ chain, IL-2 and IL-4 together regulate cell differentiation, promote the formation of immune cells, improve the killing activity of cytotoxic T lymphocyte (CTL) and NK cells, and play an important role in inflammation and cancers." (PMID 34712741, 2021). "Additionally, IFN-γ/IL-4 and TNF-α/IL-4 ratios were significantly higher in cancer patients." (PMID 34012451, 2021). "Immunosuppressive interleukins (IL)-4 and 13 may directly promote cancer but neither their status nor role in gastrointestinal tract is clarified." (PMID 32512917, 2020). "The pathways involved in IL-4 between the RA and No-RA groups included cytokine-cytokine receptor interaction, Th1 and Th2 cell differentiation, Th17 cell differentiation, T cell receptor signaling pathway, pathways in cancer, and hematopoietic cell lineage." (PMID 33426089, 2020). "mDCs manufactured using GM-CSF and IL-4 primed with OK-432 for clinical use expressed the HLA−ABC+DR+CD40+CD80+CD86+CD197+ phenotype, harboring bioactive functions that could be useful in providing personalized vaccines for cancer immunotherapy." (PMID 31546936, 2019). "Moreover, there is a negative correlation between expression of Sdc-1 mRNA and IL-4, IL-17 and Foxp3 mRNA levels in carcinoma tissues of IBC and that correlation was reversed in non-IBC." (PMID 31145753, 2019). "Interestingly, qPCR revealed that there was a negative correlation between Syndecan-1 and each of IL-4, IL-17, and Foxp3 mRNA expression in carcinoma tissues of IBC and that the correlation was reversed in non-IBC." (PMID 31145753, 2019). "Tailoring the AAb profiling with a systems biology approach provides an excellent image of the network of AAbs targeting proteins which may be key drivers of cancer-interacting SPs such as PLD, PI3K-Akt, MAPK, EGF/EGFR, c-Met, Ras, DDR, IL-4, IL-6, and TGF-β SPs in the NSCLC and SM groups." (PMID 29062084, 2017). "IL-4 triggered expression of hyaluronan synthase 3 (HAS3) may facilitate the adhesion and migration of activated immune cells and cancer cells during inflammatory response and cancer metastasis, respectively." (PMID 27214384, 2016). "However, the IR-induced microenvironment modification effect of IL-4 signaling on tumorigenicity, stemness maintenance, and metastasis of cancer cells has not been fully established." (PMID 27895317, 2016). "Our study revealed that IL-4 antagonized the stimulatory effect of TNF-α on DC’s migratory and immuno-stimulatory functions in vitro, an effect that might impair the potential efficacy of DCs used as vaccines for cancer immunotherapy in vivo." (PMID 27080531, 2016). "Interestingly, we found that TGF-β1, TGF-β2 and TGF-β3 mRNAs were all remarkably up-regulated in the co-cultured cancer cells and NFs using real-time PCR, whereas IL-4, IL-13, BMP2 and PDGF-bb mRNAs were not affected in these cells." (PMID 26857387, 2016). "The observed lack of membrane-bound IL-15 on “gold-standard” IL-4 DCs and their consequent inability to effectively promote NK cell cytotoxicity may have important implications for the future design of DC-based cancer vaccine studies." (PMID 25951230, 2015).
cancer (continued). "In addition, the higher ratios of IFNα2 to Th2 cytokines, including IFNα2/IL4, IFNα2/IL10, IFNα2/CCL2, IFNα2/CCL7, IFNα2/CCL11, and IFNα2/TNFα, were associated with increased odds of ER negative vs. ER positive cancer." (PMID 24473087, 2014). "Therefore, we examined expression of IL-17, Foxp3, IL-4 and Sdc-1 transcript levels in carcinoma tissue of non-IBC and IBC patients and tested whether there is any correlation among them." (PMID 31145753, 2019). "When we cocultured APG-2575-treated cancer cells with IL-4-activated macrophages, APG-2575-treated cancer cells did not alter the expression of CD86 and CD206." (PMID 38062129, 2024). "In a related study, DCs from cancer patients generated from CD14+monocytes by culturing with GM-CSF and IFN-α, but without IL-4 secreted higher levels of IL-10 (Th2 response), compared with IL-4 and GM-CSF generated DCs." (PMID 18588665, 2008). "This study included both pro‐inflammatory (IL‐1B, IL‐6, IL‐8, IL‐12 (p40, p70), TNF‐α, and IFN‐γ), and anti‐inflammatory (IL‐4, IL‐6, IL‐10, TGF‐β), peripheral cytokine blood serum markers with no significant findings evident between cancer survivors and matched controls." (PMID 37751068, 2023). "IL-4 and IFN-γ mRNA showed the highest upregulation in growing LLC cancers, with increased expression of 137-fold (p < 0.001) and 35-fold (p < 0.0001), respectively, compared to controls (lungs with no cancers)." (PMID 35655772, 2022). "Interestingly and similar to the data obtained from cancer secretomes, CCR8+ Tregs secreted less cytokines than CCR8- Tregs, whereas CCR8+ Teff secrete IL-4, but not IFN-γ and IL-17." (PMID 34025655, 2021). "Moreover, whereas we identified the effects of the overall inflammatory mediators on cancer incidence through DII, we did not observe the effects of individual inflammatory markers such as hs-CRP, IL-1β, IL-4, IL-6, IL-10 or (TNF)-α." (PMID 31652856, 2019). "Although no statistical difference for expression of IL-4, IL-17 and Foxp3 mRNA levels in carcinoma tissues of non-IBC and IBC patients was observed, there was a trend for upregulation of IL-4 and downregulation of Foxp3 mRNA levels in carcinoma tissues of IBC in comparison to non-IBC." (PMID 31145753, 2019). "In addition to CSF1, IL-4 from CD4+ T cells is necessary to activate TAMs to produce EGF and without CD4+ T cells, TAMs are unable to induce cancer cell migration and metastasis." (PMID 29220404, 2017). "Significantly fewer IL-4+ cells were observed in OSCC than in OLP and OLK tissues, suggesting that IL-4 might not be a key factor for immunosuppression in the cancer microenvironment." (PMID 28053372, 2016). "In addition, immunofluorescence of mouse subcutaneous cancer specimens showed that macrophage marker F4/80 was not significantly different among the groups, while M2 macrophage marker CD206 was upregulated in the two groups injected with IL-4." (PMID 39003253, 2024). "However with the exception of TGF-β, we found no consistent significant increases in IL-10, IL-4, Il-13, Il-6, GM-CSF, G-CSF, or VEGF in the blood that could account for the failure across cancer patients." (PMID 31462392, 2019). "In addition, although IL-4 exhibited a proliferation inhibition effects in vitro of RCC, the clinical use of IL-4 as an administrated agent failed to inhibit the progression of RCC and other cancers." (PMID 29137245, 2017). "Notably, after knocking down STAT6 in macrophages, the expression of CD206 stimulated by IL-4 was not reduced by 23-HBA, and 23-HBA failed to inhibit the activation of the IL-10/STAT3/Bcl-2 signaling pathway induced by M2 macrophages and the resulting resistance to 5-FU in cancer cells." (PMID 38554148, 2024).